HMGB1 (high mobility group box 1)
Diseases named in the same sentence as HMGB1 in open-access papers (continued):
Sharing a sentence is not in itself a finding about the gene and the disease.
glioblastoma (continued). "MIR-218 may negatively regulate the HMGB1/RAGE axis by targeting HMGB1, thereby inhibiting the invasion of glioblastoma cells." (PMID 38529373, 2024). "Glioblastoma treatment with the anticancer drug epidermal growth factor receptor‐targeted diphtheria toxin (DT‐ EGF) induces autophagy and HMGB1 release from tumor cells, and HMGB1 release is greatly reduced with autophagy inhibition." (PMID 37062906, 2023). "As HMGB1 promotes cancer cell growth by acting as an autocrine factor in human glioblastoma T98G and U87MG cells, we examined whether supplemental HMGB1 stimulates the proliferation of HCT116 cells." (PMID 35408786, 2022). "Tumor research has shown that exposure to PPV in human glioblastoma multiforme (GBM), uppsala 87 malignant glioma (U87MG) and human glioblastoma multiforma tumor (T98G) cell lines inhibits the interaction between HMGB1 and RAGE and suggests that PPV functions as a RAGE suppressor." (PMID 36359780, 2022). "Papaverine potently disrupted the interaction between high mobility group box 1 (HMGB1) and the receptor for advanced glycation end-products (RAGE), which was thought to be the essential mechanism of its anti-proliferative action against glioblastoma cells." (PMID 34575827, 2021). "In contrast, the amount of extracellular HMGB1 was not significantly altered after exposure of the glioblastoma cell line U87MG to fractionated RT and/or CT." (PMID 24678590, 2014). "Moreover, to better elucidate target molecules involved in malignant glioma responses, we attempted to identify danger signals like high mobility group box-1 (HMGB1) protein and heat-shock protein 70 (HSP70) in glioblastoma using cell culture system." (PMID 25097859, 2014). "Moreover, functional analyses have unveiled the involvement of NETs in the proliferation and invasive behaviors of glioblastoma multiforme (GBM) cells, facilitated by the interaction between high mobility group box 1 (HMGB1) and the receptor for advanced glycation end products (RAGE)." (PMID 38732975, 2024). "RT fractionation with 2 Gy during five consecutive days in glioblastoma (GBM) models led to enhanced secretion of HSP-70 and model-dependent HMGB1 secretion." (PMID 33806808, 2021). "The release of HMGB1 as a result of viral-derived ganciclovir tumor cell death activates TLR2 on DCs (immunogenic cell death), resulting in an efficient processing and cross-presentation of tumor antigens leading to tumor regression in a glioblastoma mouse model." (PMID 31695691, 2019). "While the amount of extracellular HMGB1 was only slightly increased in T98G and U251MG cells especially after combination of RT with VPA, fractionated RT in general resulted in increased extracellular concentrations of Hsp70 in all examined glioblastoma cell lines." (PMID 24678590, 2014). "Fisetin and quercetin did not markedly change the protein levels of HMGB1, HSP72, or KEAP1 in microglia and glioblastoma, but did modulate key protein–protein interactions." (PMID 38132142, 2023).
acute pancreatitis (45 papers, 2007 to 2025). An acute inflammatory process that leads to necrosis of the pancreatic parenchyma. "Acute pancreatitis, a disease most often caused by obstructing biliary stones or excessive alcohol use, has shown evidence of HMGB1 release by necrotic pancreatic acinar cells." (PMID 40406124, 2025). "The release of HMGB1 is closely linked to the development of various diseases, including acute pancreatitis and gastrointestinal injury." (PMID 40688353, 2025). "These facts imply that HMGB1 contributes to the pathogenesis of acute pancreatitis-associated SIRS, including acute lung injury." (PMID 29847178, 2018). "(2013) previously reported that the downregulation of HMGB1 protected against the development of acute lung injury associated with acute pancreatitis via inhibiting NF-κB activation in the lungs." (PMID 29847178, 2018). "HMGB1 especially has a high specificity (100%) and sensitivity (93%) for acute pancreatitis at 0.84 ng/ml." (PMID 40406124, 2025). "ARNTL prevents experimental acute pancreatitis by blocking the release of HMGB1 mediated by ferroptosis, revealing a new link between the circadian clock and ferritin response in inflammation and pancreatic injury." (PMID 40072057, 2025). "In acute pancreatitis, HMGB1 upregulation promotes the activation of the NLRP3 inflammasome, leading to the release of pro-inflammatory cytokines, including IL-1β, which further exacerbates pancreatic injury." (PMID 40688353, 2025). "In contrast, in Arntl-deficient mice, lipstatin-1 (a ferroptosis inhibitor) or anti-HMGB1 neutralizing antibody alleviated the development of acute pancreatitis." (PMID 39769097, 2024). "The circadian transcription factor ARNTL (also known as BMAL1) prevents experimental acute pancreatitis by blocking the ferroptosis-mediated release of HMGB1 (a sterile inflammatory mediator)." (PMID 39769097, 2024). "In acute pancreatitis experiments, it was determined that Bmal-1 plays a protective role by mitigating inflammatory injury through the inhibition of ferroptosis-mediated HMGB1 release." (PMID 39296207, 2024). "HMGB1 plays a critical role in bacterial translocation in the gut and in systemic inflammation during severe acute pancreatitis (SAP)." (PMID 33925132, 2021). "Other studies have shown that anti-HMGB1 treatment protected against renal injury in experimental acute pancreatitis." (PMID 30515205, 2018). "The HMGB1 level in pancreas and plasma were significantly increased by the induction of acute pancreatitis." (PMID 29847178, 2018). "Since damage-associated molecular patterns, such as HMGB1, contribute to linking between acute pancreatitis and distal organ injuries, we also evaluated HMGB1 levels in both the pancreas and plasma of the acute pancreatitis model mice." (PMID 29847178, 2018). "Toll-like receptor 4 (TLR4) is a pattern recognition receptor that has been noted to respond to endogenous ligands such as high mobility group box 1 (HMGB1) protein and or exogenous ligands such as lipopolysaccharide both of which can be present during the progression of acute pancreatitis." (PMID 38585277, 2024). "During the early phase of acute pancreatitis, HMGB1 may stimulate pancreatic pain by targeting CXCL12/CXCR4 and triggering RAGE signaling." (PMID 33925132, 2021). "Animal models and a number of clinical studies have shown that HMGB1, TLR4, and NF-κB are involved in the process of intestinal mucosal injury caused by intestinal ischemia-reperfusion injury, indomethacin and acute pancreatitis, all of which play important roles." (PMID 35185593, 2021). "Another study showed that the depletion of Arntl, a circadian transcription factor, contributed to increased HMGB1 release and neutrophils recruitment and induced acute pancreatitis, which could be attenuated by anti-HMGB1 neutralizing antibodies and ferroptosis inhibitors." (PMID 37325669, 2023). "Therefore, CO-HbV may decrease the pathogenesis of acute pancreatitis through the HMGB1/TLR-4 pathway." (PMID 29847178, 2018).
acute pancreatitis (continued). "HMGB1 and soluble RAGE (sRAGE), a product of RAGE activation, are elevated in patients hospitalized for acute pancreatitis, with increasing elevation attributed to increasing severity of disease." (PMID 40406124, 2025). "High mobility group box 1 protein, HMGB-1; Acetylcholinesterase, AChE; Mild acute pan crea titis, MAP; Moderation to severe acute pancreatitis, MSAP; Severe acute pancreatitis, SAP." (PMID 40821625, 2025). "The HMGB1/TLR4/NF-κB pathway also participates in indomethacin- and acute pancreatitis-induced intestinal mucosal injury." (PMID 35185593, 2021). "HMGB1 also significantly contributes to hemorrhagic shock-related acute lung injury (ALI), hyperoxia-induced ALI, and severe acute pancreatitis-related ALI." (PMID 28694564, 2017). "HMGB1 is also found to significantly contribute to hemorrhagic shock related acute lung injury (ALI); hypoxia-induced ALI and severe acute pancreatitis related ALI." (PMID 27980458, 2016). "The production of HMGB1 and its signaling through TLR4 has been shown to be especially important in the progression of severe acute pancreatitis as administration of HMGB1 to mice resulted in increased pancreatic injury and NF-ΚB signaling that could be attenuated in TLR4-deficient mice." (PMID 38585277, 2024).
heart failure (43 papers, 2011 to 2025). Inability of the heart to pump blood at an adequate rate to meet tissue metabolic requirements. "HMGB1, which serves as an early promoter and facilitator of inflammation, can cause various inflammatory responses, tissue regeneration, and heart failure." (PMID 35571117, 2022). "Loss of HMGB1 in cardiomyocytes altered glucocorticoid effects, impaired metabolic processes, and eventually resulted in small heart size and heart failure." (PMID 33101708, 2020). "Moreover, the decrease of nuclear HMGB1 was reported to be associated with human heart failure, and preserved amounts of nuclear HMGB1 could prevent cardiac hypertrophy." (PMID 27563308, 2016). "This study by Peng and colleagues demonstrated the key role HMGB1 plays in cardiomyopathy and heart failure." (PMID 37484982, 2023). "In vivo, using a murine model of heart failure, intramyocardial HMGB1 injection attenuated LV remodeling most likely through the inhibition of TGF β/Smad signaling pathway known to play an important role in the pathogenesis of cardiac remodeling and fibrosis." (PMID 35053332, 2022). "Meanwhile, miR-129-5p lightens oxidative stress and inflammation in heart failure via combining with high mobility group box-1 (HMGB1) protein." (PMID 35659193, 2022). "High mobility group box 1 (HMGB1) and Troponin T are important mediators of myocardial inflammation and heart failure." (PMID 34226512, 2021). "For example, injection of box A, an inhibitory domain HMGB1, into the heart can reverse cardiac hypertrophy and delay heart failure induced by pressure overload." (PMID 33324685, 2020). "Accordingly, studies have elucidated the role of increased serum HMGB1 concentration in acute coronary syndrome, atherosclerosis, heart failure, and other cardiovascular diseases as a marker for inflammatory response and detrimental outcome." (PMID 32286371, 2020). "The corresponding optimal cut-off value of HMGB1 concentration was 4.905 ng/ml in the current study, which is similar to those reported in ST-elevation myocardial infarction or heart failure patients." (PMID 32286371, 2020). "Our results suggest that HMGB1-RAGE axis is a redundant inflammatory factor in pressure-overload induced heart failure." (PMID 27355349, 2016). "HMGB1 has been shown to induce calcineurin-mediated cell hypertrophy in neonatal rat cardiomyocytes, while upregulated-HMGB1 under pressure overload promoted cardiac hypertrophy and heart failure." (PMID 27355349, 2016). "HMGB1 has been thought to play important roles in cardiomyocyte apoptosis induced by cardiac ischaemia-reperfusion and heart failure." (PMID 25210949, 2014). "We thus studied the role of extracellular HMGB1 in the effect of BMC transplantation for heart failure." (PMID 24204700, 2013). "Furthermore, the AGEs/High Mobility Group Box 1 (HMGB1)-RAGE axis is involved in heart failure, abdominal aortic aneurysm (AAA), and vascular calcification." (PMID 40869077, 2025). "The function of high-mobility group box 1 (HMGB1) protein depends upon its location, and extracellular HMGB1 works as a delayed mediator of proinflammatory cytokines in the initiation and amplification of inflammatory responses, whereas nuclear HMGB1 prevents cardiac hypertrophy and heart failure." (PMID 36724021, 2023). "HMGB1 is critical to the development of heart failure, and studies in human patients will be crucial to define its exact role in cardiomyocytes and pathological remodeling and how that can be exploited in the management of heart failure." (PMID 37484982, 2023). "Interestingly, cardiac hypertrophy and heart failure can be prevented when stable nuclear HMGB1 levels are maintained, it is due to HMGB1 in the nucleus attenuating DNA damage." (PMID 33324685, 2020). "Moreover, AGEs/high mobility group box-1 (HMGB-1)—RAGE interaction is described as connected with heart failure and AAA." (PMID 32231084, 2020).
heart failure (continued). "In this study, we found that HMGB1 deletion by cTnT-Cre in mouse hearts altered glucocorticoid receptor (GR) function and glycolipid metabolism, eventually leading to growth retardation, small heart and heart failure." (PMID 33101708, 2020). "Systemic administration of HMGB1 induced angiogenesis and reduced fibrosis by recruiting PDGFRα+ mesenchymal cells from the bone marrow, suggesting that HMGB1 administration might be a new therapeutic approach for heart failure after MI." (PMID 32275672, 2020). "Recent report demonstrated that HMGB1-RAGE axis is involved in the pathogenesis of inflammatory cardiomyopathy in mice with troponin I immunization, while it is well known that inflammation is also closely associated with heart failure." (PMID 27355349, 2016). "Besides that, a clinical study showed increased serum HMGB-1 in heart failure patients which was related to the severity of heart failure in diabetic patients." (PMID 27847406, 2016). "Extracellular HMGB1 is regarded as a delayed mediator of proinflammatory cytokines for initiating and amplifying inflammatory responses, whereas nuclear HMGB1 has been found to prevent cardiac hypertrophy and heart failure." (PMID 24523730, 2014). "Additionally, maintenance of stable nuclear HMGB1 levels has emerged as a potential treatment for cardiac hypertrophy because HMGB1 overexpression in the nucleus can prevent hypertrophy and heart failure by inhibiting DNA damage." (PMID 24523730, 2014). "Also, elevated levels of HMGB1 have been correlated with the disease severity of heart failure." (PMID 27059056, 2016). "Thus, there is a close link between HMGB-1 and heart failure." (PMID 27847406, 2016). "We can suggest that HMGB1, even at the mRNA level, may be a predictor of LV enlargement, severe LV dilatation, impaired systolic function, and adverse LV remodeling after MI, independently of myocardial infarct size, which may eventually lead to heart failure, arrhythmia, and poor clinical outcomes." (PMID 39457420, 2024). "During heart failure, multiple endogenous DAMPs, including the intracellular S100 proteins, heat shock protein, HMGB1 (high-mobility group box 1), and mtDNA, are released and recognized by TLRs to induce an NF-κB-dependent inflammatory response." (PMID 29511093, 2018). "High glucose concentrations induce HMGB1 secretion from different sources, and this cytokine has been associated with an increased incidence of coronary artery disease and heart failure in T2DM patients, proposing an important role of HMGB1 in the pathogenesis of T2DM and its complications." (PMID 34360753, 2021). "In summary, our results demonstrated that extracellular HMGB1, which is derived from dead donor cells at least in part, plays a role of the effect of BMC transplantation to recover the damaged tissue by favorably modulating innate immunity in heart failure." (PMID 24204700, 2013). "Previous studies of HMGB1 have centered almost exclusively on its role in the activation of inflammatory receptors, such as the receptor for advanced glycation end-products (RAGE), though this effect may be relevant in multiple pathologies, including heart failure and certain cancers." (PMID 28531105, 2017).
Insulin resistance (43 papers, 2013 to 2026). Increased resistance towards insulin, that is, diminished effectiveness of insulin in reducing blood glucose levels. "In these studies, serum HMGB1 levels directly correlated with plasma insulin levels, suggesting an association with insulin resistance." (PMID 37256493, 2023). "In conclusion, this study demonstrates a protective role of FBXW7 in the development and progression of NAFLD by attenuating inflammation and consequent insulin resistance, which is associated with the suppression of HMGB1-mediated innate immune signaling." (PMID 31215394, 2019). "A multiple linear regression analysis showed both plasma CTRP-3 and HMGB-1 concentrations were independently associated with homeostasis model assessment for insulin resistance (HOMA-IR) and interleukin-6 (IL-6) (P < 0.05 for all)." (PMID 27738641, 2016). "We can thus hypothesize that HMGB1 might participate in one of the numerous vicious circles underlying the pathophysiology of insulin resistance in PCOS." (PMID 37256493, 2023). "However, in women with PCOS, HMGB1 levels show an independent association with insulin resistance, and increase during short-term hyperinsulinemia." (PMID 37256493, 2023). "The augmented levels of INF-γ were linked to higher levels of insulin resistance, and HMGB1 and IL-2 co-treatment could increase the release of IFN-γ in PBMCs and NK-cells, as already reported." (PMID 34360753, 2021). "Similarly, work in SW872 fat cells showed that HMGB1 can serve as an adipokine, which often cause insulin resistance." (PMID 28542588, 2017). "Therefore, HMGB1 contributes also to metabolic dysfunction linked to insulin resistance." (PMID 31835864, 2019). "Thus, while the actions of HMGB1 on insulin resistance remain understudied, work from multiple systems suggests that HMGB1 can regulate TNFα and that HMGB1 can be linked to members of the insulin resistance pathway." (PMID 28542588, 2017). "Hence, HMGB1 might be involved in the development of insulin resistance via activating NF-κB signaling and associated with a raised expression of proinflammation mediators." (PMID 28101517, 2016). "In PCOS patients with comorbid insulin resistance (IR), High mobility group box 1 (HMGB1) levels in follicular fluid are significantly elevated, accompanied by enhanced autophagy in granulosa cells." (PMID 40791986, 2025). "It has been recommended that the control of HMGB1 production is probably useful to ameliorate insulin resistance in granulosa cells of PCOS patients." (PMID 39859066, 2025). "Meanwhile, high-mobility group box 1 (HMGB1), as a critical proinflammatory mediator, exacerbates insulin resistance through activation of the TLR4/NF-κB pathway." (PMID 40458174, 2025). "Blocking the autophagy pathway reverses HMGB1-induced insulin resistance effects, suggesting that elevated HMGB1 levels promote the development of insulin resistance in granulosa cells of PCOS patients through exacerbated autophagy." (PMID 40791986, 2025). "Specifically, we will review and update the understanding of HMGB-1 and its inflammatory pathways in insulin resistance, diabetic nephropathy, diabetic neuropathy, and diabetic retinopathy." (PMID 39271468, 2024). "In human ovarian cells (Polycystic ovarian syndrome- PCOS) aberrant autophagy induction upon release of the high mobility group box 1(HMGB1) plays a role in achieving insulin resistance by downregulating IRS-1, AKT, and GLUT4 translocation." (PMID 38347575, 2024). "Our results that galantamine treatment reduced inflammatory cytokines (TNF-α, IL-6, HMGB-1), improved insulin resistance and glycemic control in the db/db mice are consistent with those of the clinical trial of galantamine in patients with metabolic syndrome." (PMID 37731032, 2023).